BDNF (brain derived neurotrophic factor)
Diseases named in the same sentence as BDNF in open-access papers (continued):
Sharing a sentence is not in itself a finding about the gene and the disease.
Stroke (continued). "Methylation tests might have clinical utility because they are non-invasive, DNA based analyses are convenient to conduct due to the amplifiable and stable nature of DNA, and are advantageous over blood BDNF levels which poorly accurately reflect brain BDNF status after stroke." (PMID 23240009, 2012). "Moreover, an unresolved but important question is whether circulating BDNF levels are modified by stroke." (PMID 22195050, 2011). "In stroke patients, circulating BDNF levels before hospital admission are unknown." (PMID 22195050, 2011). "Stroke rehabilitation with different exercise paradigms has been investigated, but which one is more effective in facilitating motor recovery and up-regulating brain neurotrophic factor (BDNF) after brain ischemia would be interesting to clinicians and patients." (PMID 21347437, 2011). "Our data suggested that BDNF could alleviate cellular injury of ischemic insult, reduce the neurologic deficits and modulate local inflammation on cellular, cytokine and nuclear factor levels in brain after stroke." (PMID 21490702, 2010). "Our previous study demonstrated that NYT, in combination with exercise, exerts neuroprotective effects by enhancing BDNF and NGF levels after stroke in rats." (PMID 40361157, 2025). "Intravenous administration of this BDNF-MAb conjugate successfully crossed the BBB and improved neurobehavioral outcomes in a rat stroke model." (PMID 40005159, 2025). "Excitotoxicity, aberrant function of survival pathways dependent on brain-derived neurotrophic factor (BDNF), and disruption of the Golgi complex are shared pathological hallmarks in relevant neurological diseases, including stroke." (PMID 40883288, 2025). "Both mild and strenuous exercise regimens can induce synaptic plasticity and improve motor and cognitive function in stroke patients by modulating the expression of relevant proteins such as GAP-43, HIF-1α, and BDNF." (PMID 40837062, 2025). "This is consistent with the results of a previous study, which found that TMS treatment reduced glioblastogenesis and promoted the expression of BDNF and NGF in the peri-infarct area after stroke." (PMID 40948655, 2025). "Immunohistochemistry is a semi-quantitative method that provides preliminary data on BDNF and VEGF contents in the infarct region and on the correlations between these protein levels and clinical stroke outcomes." (PMID 41465442, 2025). "Signaling by brain-derived neurotrophic factor (BDNF)-binding to its high-affinity transmembrane receptor, tropomyosin-related kinase B (TrkB), becomes profoundly aberrant in stroke 9,10." (PMID 40225562, 2025). "Angiogenesis is a critical protective mechanism for neuroregeneration after stroke, and stem cell therapies promote it primarily through the bystander effect by secreting growth factors (e.g., VEGF, BDNF, IGF‐1, Ang‐1)." (PMID 41427019, 2025). "Irisin has recently been noticed as one of the main factors influencing neurogenesis pathways such as BDNF and ERK1/2/AKT after stroke." (PMID 40896700, 2025). "It highlighted the critical functions of brain-derived neurotrophic factor (BDNF) and pro-inflammatory cytokines in post-stroke recovery, suggesting that these factors are central to the recovery process." (PMID 40896336, 2025). "Gut microbiota also influences neurotrophic factors such as brain-derived neurotrophic factor (BDNF) and glial cell-derived neurotrophic factor (GDNF), involved in recovery after stroke." (PMID 41155363, 2025). "Next, in stroke cynomolgus monkeys and rats, muscle atrophy, FNDC5/irisin/BDNF expression, and cognition were measured." (PMID 41201499, 2025). "Similarly, upregulation of BDNF might positively contribute to recovery through stimulation of neuroplasticity and neurogenesis, further supporting the potential of hypercapnic hypoxia as a modulator of reparative processes in the post-stroke brain." (PMID 41465442, 2025).
Stroke (continued). "In this study, exercises were started 24 hr after the stroke, and 5 sessions were performed in one week, and the results showed that BDNF and tyrosine kinase B values were 71.5% and 83%, respectively increased in the CTID group compared to the stroke group." (PMID 40896700, 2025). "Examples of sample sizes in BDNF and APOE genetic studies on stroke outcome and recovery from 2016 and later." (PMID 40215404, 2025). "Thus, the elevated BDNF and TrkB levels in the early stage of stroke in our study may constitute an adaptive and neuroprotective strategy in response to various types of neuronal insult, which can also be found in diseases associated with cognitive dysfunction." (PMID 41181681, 2025). "In our study, we performed immunohistochemical analysis to investigate the roles of BDNF and VEGF in post-stroke recovery following gas exposure." (PMID 41465442, 2025). "In addition, atorvastatin may promote functional recovery in stroke by increasing BDNF expression." (PMID 40358798, 2025). "The secondary outcomes include The Stroke and Aphasia Quality of Life Scale (SAQOL-39 g), resting-state electroencephalogram (resting-state EEG), Event-related potentials (ERP), brain derived neurotrophic factor (BDNF)." (PMID 38725649, 2024). "Thus, herein, we review evidence from both preclinical and clinical studies of BDNF in pediatric ABI, focusing on three key insults, namely, TBI, global cerebral ischemia, and stroke, suggesting that peripheral BDNF concentrations, genotype, and DNAm may be markers of survival and recovery." (PMID 38397427, 2024). "In this study, RIC was associated with increased cerebral blood flow velocity, reduced MMP-9 and increased BDNF suggesting that improved cerebral perfusion, blood–brain barrier integrity and neurogenesis may underlie the effect of long-term RIC in neurological recovery after stroke." (PMID 39702489, 2024). "Stroke-triggered inflammation notably impacts HPA axis functionality and curtails BDNF expression, thereby influencing synaptic plasticity." (PMID 38377025, 2024). "Inhibiting BDNF blocks AMPA receptors and AMPA-mediated motor recovery following stroke in a mouse model compared to controls." (PMID 38397427, 2024). "Therefore, BDNF supplementation may be beneficial in patients with severe stroke symptoms." (PMID 38707431, 2024). "It was proved, in studies involving rodent models of stroke and traumatic brain injury (TBI), that the activation of nerve growth factor (NGF) and brain-derived neurotrophic factor (BDNF) signaling promotes neuroprotection, synaptogenesis, and neurogenesis." (PMID 38397420, 2024). "Optogenetic stimulations post-stroke resulted in a beneficial increase in NGF, BDNF, and GAP-43 levels." (PMID 38397420, 2024). "In patients with stroke, the patient who had the high levels of CD8+ BDNF+ T cells had the highest levels of BDNF+ Tregs." (PMID 37563735, 2023). "So, we assessed the BDNF level in children with SCD and its relation to neurological complication as silent stroke." (PMID 36774398, 2023). "The present study preliminarily deduced that serum BDNF, NE, ET and glutamate, and peripheral blood SOD, ALB, HB, and CAT can be used as indicators of functional recovery in stroke patients." (PMID 37731856, 2023). "As neuromodulators, BDNF, pro-BDNF, and MMP-9 are closely related to the recovery of neurological and psychiatric diseases such as stroke." (PMID 37735708, 2023). "In another Middle Cerebral Artery Occlusion (MCAO) model of stroke, auricular VNS enhanced BDNF gene expression in the rat brain, suggesting that it is one of the factors that promotes angiogenesis." (PMID 37106754, 2023). "This indicates that serum BDNF can be used as a biomarker for NIBS treatment, and that this can be used to predict the improvement of stroke function." (PMID 37731856, 2023). "Basically, BDNF can protect neurons against various insults and the neuroprotection of P2X4R after stroke by promoting the synthesis of mBDNF." (PMID 35821455, 2023).
Stroke (continued). "The robust reduction in BDNF levels found in most studies where acute ischemic stroke patients are compared to controls, combined with the known neuroprotective/neurodegenerative effects of BDNF, suggest that means to increase BDNF levels may be effective therapeutic targets in stroke." (PMID 35756121, 2022). "Further research is needed to elucidate the factors that influence changes in BDNF, GDNF and IGF-II levels in people with stroke receiving physical therapy and chiropractic adjustments." (PMID 36556107, 2022). "To date, no studies have evaluated the effects chiropractic care on serum brain-derived neurotrophic factor (BDNF), insulin-like growth factor-II (IGF-II) and glial cell-derived neurotrophic factor (GDNF) in people with stroke." (PMID 36556107, 2022). "PEA was able to prevent the plasmatic reduction of the brain-derived neurotrophic factor (BDNF) and glial cell line-derived neurotrophic factor (GDNF) in a murine model of stroke, thus explaining, at least in part, its neuroprotective effects." (PMID 35740883, 2022). "The neurotrophic factors transcripts including BDNF, GDNF, NGF, and NT‐3 were measured 7‐day post‐stroke." (PMID 35715988, 2022). "Thus, a blockade of the BDNF-TrkB signaling pathway by the TrkB inhibitor ANA-12 can abolish the protective effect of sEH gene deletion in the middle cerebral arterial occlusion (MCAO) models of stroke, suggesting the role of BDNF-TrkB signaling in the actions of sEH inhibitors." (PMID 35563342, 2022). "This review will outline the current state of preclinical and clinical research surrounding the potential for BDNF and NGF to become treatment options for patients following stroke." (PMID 35283994, 2022). "Brain-derived neurotrophic factor (BDNF) is a recognized marker of neuroplasticity, and as such was included as a potential marker of stroke recovery." (PMID 36009129, 2022). "These secondary RCT outcomes represent the first multi-session study to evaluate the effects of chiropractic adjustments on serum BDNF, IGF-II and GDNF in people with stroke." (PMID 36556107, 2022). "However, sex differences in the expression of brain-derived neurotrophic factor, which has been shown to affect memory, learning, and stroke severity through its actions on neuronal and synaptic plasticity, may potentially explain sex differences in post stroke cognitive decline." (PMID 35522611, 2022). "In Wistar rats, TGF-β and BDNF/TrkB levels were increased solely 24-h after photothrombotic stroke (TGF-β (F = 6.864 *p ≤ 0.05); BDNF (F = 5.734 *p ≤ 0.05) and TrkB (F = 115.3 *p ≤ 0.05))." (PMID 34408211, 2021). "Therefore, Rhy may downregulate the BDNF pathway under some conditions of neuronal activation such as epilepsy or after ketamine administration, while it may upregulate it in specific pathological conditions such as stroke, stress or Tourette syndrome." (PMID 34207633, 2021). "In the present study, we took tissue blocks for the BDNF measurement lateral to the stroke, because the goal was to determine if PDE10A inhibition activated BDNF in sensorimotor projections to the striatum." (PMID 32378029, 2021). "The BDNF mRNA levels were significantly higher in the brain tissues of the TXC-treated animals compared with the untreated controls at 7 and 14 days post-stroke." (PMID 34212980, 2021). "Specifically, the intense exercise protocol showed a significant increase in the mRNA expressions of HIF-1α, TrkB, CREB, BDNF, and NGF at different time points as compared to the stroke groups." (PMID 33625674, 2021). "In our cross-sectional study, we are unable to determine the trend of NRG-1, BDNF, PDGF-AA, versus cerebral arteriopathy or progression to stroke over time for these subjects." (PMID 35935682, 2021).
Stroke (continued). "In addition, animal studies have revealed a strong association between decreased BDNF levels and increased post-stroke depressive-like behaviors, and lowered serum BDNF levels were reported in stroke human patients, supporting the hypothesis that BDNF may be related to PSD." (PMID 34141514, 2021). "BDNF is key in understanding PSD and the complex interactions between antidepressants and post-stroke recovery." (PMID 34759285, 2021). "Key predicted upstream regulators include BDNF, which has been shown to be produced by MSCs and has been identified as a mechanism of MSC protection of neurons in stroke models." (PMID 34887728, 2021). "Three additional studies reported the relationship between BDNF and NIHSS during the acute stroke phase." (PMID 33809965, 2021). "In summary, in Wistar rats, IL-1β, IL-6, TGF-β, BDNF/TrkB and VEGF levels were increased at 24-h after stroke, IL-10 was increased at 30 days." (PMID 34408211, 2021). "Twenty-five studies reported both the serum BDNF levels and the NIHSS during the acute stroke phase." (PMID 33809965, 2021). "In rodent models of stroke and TBI, the activation of NGF and BDNF signaling was shown to promote neuroprotection, synaptogenesis, and neurogenesis." (PMID 33015061, 2020). "Exercise-induced neuroplasticity, characterized by inhibited apoptosis and increased neurogenesis and brain-derived neurotrophic factor (BDNF), facilitates recovery from brain damage after traumatic brain injury, ischemia, and stroke." (PMID 32384696, 2020). "Altered neuronal plasticity such as suppressed long-term potentiation (LTP), reduced BDNF and oxytocin signaling, and disturbed dopamine synthesis/uptake were detected in the prefrontal cortex (PFC) during the chronic phase after stroke." (PMID 32010477, 2020). "Galectin-1 has been demonstrated to promote astrocyte-derived BDNF secretion and functional recovery in a rat stroke model; evidence from the LPS-induced neuro-inflammation model suggest that the potential mechanism might be attributed to the immunoregulatory function of BDNF on microglia responses." (PMID 33042113, 2020). "In the experimental model of stroke, the pretreatment with flaxseed oil that contains mainly ALA and linoleic acid (n-6 PUFA) increased the level of BDNF in the cortex." (PMID 33343231, 2020). "This difference might be due to seven deaths caused by ischemic heart disease in the low BDNF group, two deaths caused by ischemic heart disease in the high BDNF group, and no deaths caused by stroke among the 22 events of all-cause mortality in the present therapy." (PMID 32679912, 2020). "A previous study showed that treatment with the conditioned medium of NPCs promoted SVZ neurogenesis following stroke, suggesting that SVZ neurogenesis can be mediated by NPCs secreting BDNF." (PMID 32269595, 2020). "Therefore, the use of new technologies to manufacture BDNF, innovative strategies to control its targeted delivery, and production of BDNF mimetics in comprehensive preclinical studies may pave the way for future clinical application of the BDNF-TrkB signaling pathway in stroke treatment." (PMID 32399020, 2020). "As mentioned in Introduction, the level of BDNF is influenced by FFAs and diet, while DGLA is increased in nonalcoholic fatty liver disease (NAFLD) in stroke patients." (PMID 33343231, 2020). "Thus, the BDNF genotype could be considered as a factor that may influence neuroplasticity, reorganization, and the functional role of white matter tracts related to motor recovery following stroke." (PMID 33029116, 2020). "A middle cerebral artery occlusion (MCAO)-induced recurrent stroke mouse model was performed to assess the effects of LIPUS on neurological function, pathological change, neuronal cell apoptosis, and BDNF induction in the brain." (PMID 31635269, 2019). "Similar to BDNF, CNTF mRNA was upregulated in reactive GFAP-positive astrocytes after entorhinal cortex lesion and stroke." (PMID 31105589, 2019).
Stroke (continued). "The EPO‐producing fibroblasts can thus secret BDNF and EPO simultaneously in the infarcted area, which enhanced the post‐stroke neurogenesis in a highly effective way." (PMID 30920178, 2019). "The expression of M1 (MCP-1, iNOS, CD32, CD86 and IFN-γ) and M2 (Ym1/2, Arg-1, CD206, BDNF and TGF-β) markers was significantly increased in vehicle-treated stroke mice 1, 3, 7, and 14 days after MCAO." (PMID 31434993, 2019). "The increase of BDNF, protein level after EMF treatment, confirmed the neuroprotective action of EMF in mice during recovery process after stroke." (PMID 30319398, 2018). "Therefore, serum levels of mature BDNF may correlate with functional levels in stroke patients." (PMID 30322026, 2018). "However, as seen during post-stroke recovery in patients undergoing physical activity, a reduced level of these harmful elevations of epinephrine and norepinephrine are seen along with improved motor function through neuroplasticity and elevated levels of BDNF." (PMID 30405992, 2018). "Since BDNF expression is CREB-regulated, this result supports the neurotrophin expression pattern observed after stroke." (PMID 28134845, 2017). "In the studies with animal models of stroke, an increase in the expression of BDNF, GDNF, HGF, EGF, FGF-2, and IGF-1, as rapidly as 12 h after the insult and lasting until 5 days after stroke, has been described." (PMID 26607630, 2016). "This is the first report to show that 2-week low-frequency rTMS increases serum levels of mature BDNF and MMP-9 in stroke patients." (PMID 27007747, 2016). "This study explored the relationships between BDNF and APOE genotype, chronic motor status, and motor improvement following a 14-day protocol of upper-limb stroke therapy." (PMID 27242654, 2016). "It reported that hydrogel-BDNF advanced immature neurons migration to IBZ and kept them survival for a long time, as well as facilitated axonal sprouting following stroke." (PMID 27465579, 2016). "Administration of gene modified SC that overexpresses neurotrophic factors like brain-derived neurotrophic factor (BDNF), Akt, and NGF can be a useful tool for neurorecovery after stroke." (PMID 26347826, 2015). "Moreover, BDNF could potentially be used to treat diseases in which alterations in its levels are not directly involved in the pathogenesis (for instance, in Parkinson’s disease, amyotrophic lateral sclerosis, stroke and spinal cord injury)." (PMID 26437780, 2015). "For example, brief daily treadmill running for 3 weeks prior to stroke reduced infarct volumes in the frontoparietal cortex and dorsolateral striatum, and these effects were correlated with upregulation of NGF and BDNF in cortical neurons and striatal glia." (PMID 24818146, 2014). "However, with the exception of BDNF in the striatum, changes in expression of these genes in response to stroke were similar between diet groups, suggesting that protection afforded by fasting and protein-free DR could work via different mechanisms or time scale." (PMID 24705386, 2014). "Six days after stroke and PTH or saline treatment, expression of regenerative factors VEGF, EPO receptor (EPOR), Ang-1, Tie-1, Flk-1, BDNF and SDF-1 in the ischemic peri-infarct region were analyzed using Western blotting." (PMID 24503654, 2014). "Erythropoietin (EPO) can enhance the neurogenesis and angiogenesis via BDNF and VEGF in rat stroke model." (PMID 24719869, 2014). "Over expression of some neuroprotective cytokines including VEGF, neurotrophin-3, BDNF, FGF-2, and GDNF has been reported to potentiate the therapeutic effects of transplanted NSCs in stroke animals." (PMID 24719869, 2014). "Recent research reveals that post-stroke angiogenesis is tightly coupled to neurogenesis and possibly mediated by the release of SDF-1, Ang-1 and BDNF from proliferating endothelial cells." (PMID 24503654, 2014). "Brain-derived neurotrophic factor (BDNF) is a major neurotrophin and promotes functional recovery and neuroprotection after stroke." (PMID 25418536, 2014).